VCAN (versican)
Diseases named in the same sentence as VCAN in open-access papers (continued):
Sharing a sentence is not in itself a finding about the gene and the disease.
lung carcinoma (12 papers, 2016 to 2023). "In the NSCLC group, we used binary logistic regression analysis to analyze the predictive risk value of lung cancer metastasis by plasma versican and plasma exosomal versican levels." (PMID 37259101, 2023). "This is in line with the investigations of versican-induced lung-cancer metastasis, in which IL6 knockout caused only small differences in survival." (PMID 36224342, 2022). "A lung cancer-derived extracellular-matrix protein versican is reported to cause a TLR2-dependent activation and M2-phenotype polarization in TAM to induce tumor metastasis." (PMID 32788720, 2020). "We further investigated whether the diagnostic performance of plasma versican and plasma exosomal versican was greater than other common lung cancer markers NSE, CEA, CYFRA21-1, and SCC in NSCLC patients with metastasis." (PMID 37259101, 2023). "The results of binary logistic regression analysis showed that high levels of plasma exosomal versican had higher predictive value for lung cancer incidence, while high levels of plasma versican had higher predictive value for lung cancer metastasis." (PMID 37259101, 2023). "The secretion of versican (VCAN) by monocytes due to their interaction with lung carcinoma cells is being reported in this study for the first time." (PMID 37784035, 2023). "Among the targeted lung‐cancer‐associated sEV makers (i.e., THSB2, VCAN, and TNC), we selected TNC for sEV capture because it was consistently expressed across the tested lung cancer cell lines used in this study." (PMID 36394090, 2022). "First, we detected higher VCAN expression in lung cancer samples at the mRNA level, which was confirmed by TCGA lung cancer database." (PMID 33430083, 2021). "Versican has been shown to be produced by lung cancer cells and activate alveolar macrophages via TLR2, TLR6 and CD14 signaling to induce TNFα and IL6 production that subsequently supports lung colonization." (PMID 33014869, 2020). "In lung cancer, versican is highly expressed in NSCLC and its expression is tightly correlated with hyaluronan." (PMID 33014869, 2020). "Markedly over-expression of THBS2 and its co-expressed genes (such as VCAN, CLO11A1, FAP) predicts poor survival of patients with lung cancer; down-regulation of VCAN and THBS2 inhibits cell proliferation in NSCLC." (PMID 28881680, 2017). "Moreover, the data revealed that VCAN expression was negatively correlated with overall survival in all patients with lung cancer and lung adenocarcinoma patients." (PMID 33430083, 2021). "However, although many studies have focused on the use of immunohistochemical (IHC) labeling of versican to detect malignancies, there has been no report on the expression of versican or its diagnostic utility in lung cancer plasma or lung cancer exosomes." (PMID 37259101, 2023). "In this study, we have demonstrated that the lung cancer cell-monocyte cross-talk modulates the secretion of IFI30, RNH1, CLEC3B, VCAN, IGFBP2, C2 and TUBB4B favoring tumor growth and metastasis." (PMID 37784035, 2023). "GraphPad Prism was used to draw the receiver operating characteristic (ROC) curves for the lung cancer markers NSE, CEA, CYFRA21-1, SCC, plasma versican, plasma exosomal versican, and the combination." (PMID 37259101, 2023). "For example, in lung cancer PMN, tumor-derived VCAN activated macrophages, generating an inflammatory environment, whereas, in the MMTV-PyMT model, the BMDC-derived VCAN was pivotal for lung PMN development." (PMID 37350937, 2023). "In conclusion, this study identifies IFI30, RNH1 and CLEC3B, VCAN, IGFBP2, C2, TUBB4B as the proteins secreted by lung carcinoma cells and monocytes respectively as a result of their mutual interaction." (PMID 37784035, 2023). "For the first time, we showed the direct binding of IRF9 to the promoter of VCAN as well as a correlation between IRF9 and VCAN expression in lung cancer." (PMID 33430083, 2021).
lung carcinoma (continued). "Based on the human lung cancer data, a positive correlation was found between IRF9 and VCAN expression." (PMID 33430083, 2021). "As anti‐TNC antibody‐functionalized nanopillars enrich cancer‐associated sEVs, we expected DECODE to provide an sEV molecular profile with higher expressions of CD63, THBS2, VCAN, and TNC in the three lung cancer cell lines and low/negligible biomarker expression from HBECs and PBS controls." (PMID 36394090, 2022). "COL5A2, MXRA5, and VCAN coexpressed with THBS2 may have significant oncogenic functions in both breast and lung cancers." (PMID 27513329, 2016). "Indeed, we demonstrated the IRF9-dependent regulation of VCAN for the first time and showed that CDKN1A might be involved in lung cancer development and progression." (PMID 33430083, 2021).
astrocytoma (11 papers, 2004 to 2023). "For example, versican enhances locomotion and reduces cell adhesion of astrocytoma cells through the binding of its G1 domain to hyaluronan." (PMID 37174618, 2023). "In astrocytoma and chondrocyte morphogenesis, the effects of versican are greatly reduced when the G3 domain or EGF-like motifs within the G3 domain were deleted." (PMID 21079779, 2010). "In astrocytoma, versican G3 enhances tumor growth by interactions with β1 integrin and angiogenic factor VEGF." (PMID 21079779, 2010). "Expression of the versican G1 domain protects sarcoma cells from apoptosis, and binding of the versican G3 domain to β-Integrin promotes survival of astrocytoma cells." (PMID 18454205, 2008). "In astrocytoma, mechanisms appear to include versican G3 interactions with β1 integrin and angiogenic factor VEGF." (PMID 17662123, 2007). "Most previous studies have demonstrated that versican expression is predictive of poor prognosis in many cancers, including breast, ovarian, cervical, prostate, endometrial, non-small cell lung cancer and astrocytoma." (PMID 31531098, 2019). "In human astrocytoma cells VCAN was shown to form a complex with fibronectin and VEGF." (PMID 26873137, 2016). "Versican exerts its effect on astrocytoma cell migration and adhesion through the G1 domain." (PMID 21079779, 2010). "Interaction of the EGFR and versican has been demonstrated for transfected astrocytoma U87 cells." (PMID 17662123, 2007). "Mechanistically, versican enhances the locomotion of astrocytoma cells and reduces cell adhesion." (PMID 17453002, 2007).
leiomyoma (11 papers, 2007 to 2025). A well-circumscribed benign smooth muscle neoplasm characterized by the presence of spindle cells with cigar-shaped nuclei, interlacing fascicles, and a whorled pattern. "For example, treatment with gonadotropin-releasing hormone analogs reduced fibromodulin expression in fibroid tissues to physiological levels, while all-trans retinoic acid suppressed leiomyoma cell proliferation by downregulating versican." (PMID 41228294, 2025). "For example, while KANK1 is substantially upregulated predominantly in SMCs, VCAN is highly expressed selectively in fibroblasts in fibroid tumors." (PMID 38326302, 2024). "The treatment of the Alba cultivar of the strawberry extract was found to inhibit the induction of collagen 1A1, fibronectin, and versican mRNA expression by activin A in leiomyoma cells." (PMID 35800452, 2022). "Human myometrial and leiomyoma cells were treated with nintedanib at 5 μM for 24 h, and mRNA and protein levels of fibrosis‐related molecules (fibronectin and versican) were measured by real time qPCR and western blot, respectively." (PMID 34323413, 2021). "It has also been observed that both extracts significantly decreased collagen 1A1, fibronectin, versican, and activin A messenger RNA expression in leiomyoma cells." (PMID 33504114, 2021). "In a previous work, we demonstrated that activin A can increase collagen1A1, fibronectin and versican expression in primary leiomyoma cells." (PMID 28212568, 2017). "In the present study, we found that Alba cultivar of strawberry extract is able to inhibit activin A induced ECM collagen1A1, fibronectin, and versican mRNA expression in leiomyoma cells." (PMID 28212568, 2017). "We found that strawberry extract significantly reduced fibronectin, collagen 1A1, and versican mRNA expression in primary myometrial and leiomyoma cells compared with untreated cells." (PMID 28212568, 2017). "Strawberry significantly decreased collagen1A1, fibronectin and versican mRNA expression in leiomyoma cells." (PMID 28212568, 2017). "The up-regulation of versican expression was reported in leiomyoma cells compared to healthy counterparts." (PMID 28212568, 2017). "Activin A, a pleiotropic growth factor, belongs to the TGF-β superfamily, has been reported to increase ECM components, including collagen1A1, fibronectin, and versican mRNA expression in leiomyoma cells." (PMID 28212568, 2017). "In the present study, we found that strawberry extract was able to inhibit ECM components, including collagen1A1, fibronectin, and versican in leiomyoma cells." (PMID 28212568, 2017). "In addition to activin A, TGF-β3 was reported to increase collagen1A1, fibronectin 1 and versican expression in both myometrial and leiomyoma cells." (PMID 28212568, 2017). "ATRA reduced the concentration of versican protein in myometrial and leiomyoma cells." (PMID 18248652, 2008). "Versican variant V2 did not demonstrate statistically significant difference in untreated leiomyoma and myometrial cells, although ATRA treatment down-regulated the mRNA expression of this variant as well (data not shown)." (PMID 18248652, 2008). "The expression of many components of ECM including collagens, decorin, versican, fibromodulin, intergrins, extracellular matrix protein 1 (ECM-1), syndecan and ESM-1 has been identified in leiomyomas as well as dermal wounds during healing, scars and keloids." (PMID 17718906, 2007). "Furthermore, strawberry was able to reduce activin A induced fibronectin, collagen1A1, and versican as well as activin A and PAI-1 mRNA expression in leiomyoma cells." (PMID 28212568, 2017). "Exposure of leiomyoma cells to ATRA resulted in a dose-dependent inhibition of templates for specific ECM protein production including collagen 1, collagen 4, fibronectin and versican." (PMID 18248652, 2008).
leiomyoma (continued). "While in leiomyoma it is well established that its growth is also due to an important increase in ECM proteins, in particular collagen 1A1, fibronectin, and versican, this is not so clear in leiomyosarcoma, although the role of ECM in soft-tissue sarcoma has been reported." (PMID 37299521, 2023).
bladder cancer (10 papers, 2017 to 2025). "Versican has been reported to be expressed in a wide range of malignancies such as ovarian, hepatocellular, colon, and bladder cancers and is associated with poor patient outcomes." (PMID 37833287, 2023). "Genome-wide methylation analysis of bladder cancer tissues discovered hypermethylation in the promoter region of a number of genes; with the combined hypermethylation of SOX1, PITX2, or versican identifying patients with a higher risk of bladder cancer morbidity." (PMID 29559954, 2018). "The VCAN, translated into the CSPG2 protein, has been reported as a marker for the metastasis of various carcinomas, including bladder carcinoma." (PMID 39688793, 2025). "Further analysis of the clinical data of VCAN according to the TCGA bladder cancer (BLCA) database showed that VCAN RNA expression was significantly higher in the LVI(+) group than in the LVI(−) group (p < 0.01)." (PMID 37108649, 2023). "We revealed a new mechanism whereby TGF-β1 dominated stromal fibroblast-mediated EMT of bladder cancer cells via the FAP/VCAN axis and identified potential biomarkers (FAP, VCAN, N-cadherin, and Vimentin) of bladder cancer." (PMID 37461061, 2023). "Above all, we revealed that the TGF-β1/FAP/VCAN axis promotes stromal fibroblast-mediated EMT in bladder cancer in cytological experiments." (PMID 37461061, 2023). "High levels of VCAN have been observed in various types of cancer, including bladder cancer and melanoma." (PMID 37108649, 2023). "As a further demonstration of the reliability of our findings, we created subcutaneous xenograft models and demonstrated that the TGF-β1/FAP/VCAN axis regulates bladder cancer EMT in vivo." (PMID 37461061, 2023). "Blocking the versican/CCL2/CCR2 signaling axis is indicated to purvey novel adjuvant strategies for detaining the emergence of clinical metastasis in bladder cancer patients." (PMID 31068944, 2019). "In addition, we demonstrated that the TGF-β1/FAP/VCAN axis regulates bladder cancer EMT in subcutaneous xenograft models." (PMID 37461061, 2023). "Previous research has found that VCAN is highly expressed in bladder cancer." (PMID 37108649, 2023). "In summary, VCAN, which regulates inflammation through the hyaluronic acid matrix, has been shown to contribute to the development and metastasis of different types of cancer, such as breast and bladder cancers." (PMID 37108649, 2023). "This work analyzes the role of versican (VCAN) on bladder cancer (BLCA)." (PMID 33604385, 2021). "Several drugs or chemicals such as cisplatin and curcumin could result in increasing the mRNA level of VCAN, which suggested that clinical treatment of bladder cancer with these drugs may induce poorer prognosis through increasing the VCAN level." (PMID 33604385, 2021). "Furthermore, an increased expression of versican V1 and V3 isoforms was positively correlated to lung metastasis in a bladder cancer murine model due to the increased release of CCL chemokine by macrophages." (PMID 31068944, 2019). "However, the expression of VCAN on human bladder cancer (BLCA) has been rarely reported." (PMID 33604385, 2021). "Versican (VCAN), a downstream molecule of FAP, plays an essential role in TGF-β1/FAP axis-induced EMT in bladder cancer cells." (PMID 37461061, 2023).
pancreatic cancer (10 papers, 2014 to 2023). "Of tumor-elevated proteins identified in LMD sampling, 4 additional tumor-associated proteins, COL17A1, VSNL1, LYPD3, and VCAN, were reported in the Pancreatic Cancer Database." (PMID 36266629, 2022). "Of 115 tumor-elevated proteins identified in LMD sampling, 4 additional tumor-associated proteins, COL17A1, VSNL1, LYPD3, and VCAN, were reported in the Pancreatic Cancer Database." (PMID 36266629, 2022). "Oncomine analysis of cancer vs. normal tissue confirmed that COL12A1, FN1, ITGA2, LAMB3, LAMC2, THBS2, and VCAN were significantly overexpressed in pancreatic cancer from different datasets." (PMID 34007003, 2021). "TGF-β1 and CM from pancreatic cancer cells synergistically suppressed decorin and lumican, and stimulated versican expression in pancreatic stellate cells." (PMID 25593993, 2014). "Moreover, in the Pei pancreas dataset, COL12A1, FN1, ITGA2, LAMB3, LAMC2, THBS2, and VCAN mRNA expression levels were higher in pancreatic cancer tissue than in normal pancreatic tissue samples." (PMID 34007003, 2021). "THBS2 and VCAN were expressed in both stromal and pancreatic cancer cells, whereas ITGA2, LAMB3, and LAMC2 were solely expressed by pancreatic cancer cells." (PMID 34007003, 2021).
cervical cancer (9 papers, 2015 to 2024). A primary or metastatic malignant neoplasm involving the cervix. "Additionally, versican overexpression was associated with decreased infiltration of CD8+ T cells in stromal compartments of cervical cancer." (PMID 27855162, 2016). "GC patients with high VCAN are often resistant to immunotherapy; in one study, cervical cancer patients who were resistant to chemotherapy also presented high expression of VCAN." (PMID 38791985, 2024). "In patients with cervical cancer with an infiltration depth greater than 15 mm, low expression of versican predicts poorer survival." (PMID 36982551, 2023). "Previous studies have reported a correlation between VCAN expression and the immune microenvironment in cervical cancer patients." (PMID 37108649, 2023). "In support of this proposition, analysis of versican expression in human cervical cancer samples has suggested that increased versican expression in stromal cells inhibited CD8+ T cell invasion, preventing CD8+ T cell clearance of tumorigenic cells." (PMID 34527702, 2021). "Versican, an ECM proteoglycan, was evaluated in cervical cancer samples by IHC and in situ hybridization." (PMID 30208169, 2018). "The expression of high levels of versican in tumor stromal myofibroblasts was associated with (I) a lower frequency of tumor-infiltrating CD8-positive T cells, (II) increased tumor parametrial invasion and infiltration depth (III) and no change in cervical cancer survival." (PMID 30208169, 2018).
breast tumors (8 papers, 2010 to 2025). "Studies have demonstrated increased VCAN accumulation in breast tumors compared to normal breast tissue." (PMID 40361362, 2025). "miR-543 has already been shown to suppress breast tumor cell viability, proliferation, and progression by repressing VCAN." (PMID 35645340, 2022). "In human breast tumors, VCAN is enriched in proliferating tumor areas and particularly in HA-rich portions." (PMID 33430083, 2021). "The high expression of versican in human breast tumor appears prognostic, is predictive of relapse, and negatively impacts overall survival rates." (PMID 22862967, 2012). "Immunolocalization of versican in breast tumors, including infiltrating ductal carcinoma, has been reported." (PMID 21079779, 2010). "The high expression of versican in human breast tumors appears prognostic, being predictive of relapse, and negatively impacting overall survival rates." (PMID 21079779, 2010). "Increased versican expression in breast tumors is predictive of relapse and has negative impact on survival rates." (PMID 21079779, 2010).
leukemia (8 papers, 2015 to 2024). A malignant (clonal) hematologic disorder, involving hematopoietic stem cells and characterized by the presence of primitive or atypical myeloid or lymphoid cells in the bone marrow and the blood. "In summary, to our knowledge, this represents the first study to demonstrate an association between high expression of EMT-related gene VCAN and leukemia cell invasive potential." (PMID 31777586, 2019). "ShRNA-mediated silencing of VCAN can significantly inhibit the migration and invasion of the leukemia cells, which means that VCAN may be the novel diagnostic and therapeutic target for AML." (PMID 33791386, 2021). "The high expression of VCAN is associated with the poor prognosis of leukemia patients." (PMID 33791386, 2021). "Moreover, high expression of VCAN played an important role in leukemia cell migration and invasion, and was potentially associated with poor overall survival of AML patients." (PMID 31777586, 2019). "Finally, we found that knockdown of VCAN significantly reduced the invasive capacity of leukemia cells, and further discovered that high expression of VCAN was associated with poor outcome in AML patients." (PMID 31777586, 2019). "Studies have shown that VCAN also acts as a core protein in the EMT, as its upregulation promotes leukemia cell invasion." (PMID 33424916, 2020). "In addition, we also found some leukaemia‐specific proteins, oncogenes (COL2A1, CLIP1, NUMA1 and GALK1), and stem cell‐regulated proteins (ACAN, VCAN, COMP and PRDX6)." (PMID 38499475, 2024). "Functional evaluations showed that silencing VCAN by shRNA significantly suppressed cell migration and invasion capacity, whereas increased VCAN by overexpressing NPM1-mA enhanced migration and invasion ability of leukemia cells." (PMID 31777586, 2019).
lung diseases (8 papers, 2008 to 2024). "For example, VCAN accumulation occurs in various human lung diseases, especially in vascular lesions in PAH." (PMID 39205715, 2024). "Some of these increased ECM proteins, such as TNC and VCAN, had been involved in tissue remodeling and, specifically, in different lung diseases that imply an altered wound healing." (PMID 25064447, 2014). "VCAN protein could interact with inflammatory cells involved in autoimmune diseases, cardiovascular and lung disease." (PMID 36569220, 2022).